KMT2A (lysine methyltransferase 2A)
Diseases named in the same sentence as KMT2A in open-access papers (continued):
Sharing a sentence is not in itself a finding about the gene and the disease.
acute lymphoblastic leukemia (190 papers, 2006 to 2025). Leukemia with an acute onset, characterized by the presence of lymphoblasts in the bone marrow and the peripheral blood. "Several other recurrent alterations, such as ETV6::RUNX1, KMT2A rearrangements, and high hyperdiploidy in childhood acute lymphoblastic leukemia, are associated with prognosis and treatment decisions." (PMID 40725438, 2025). "AML or acute lymphoblastic leukemia (ALL) with KMT2A gene rearrangement (r), AML with NPM1 mutation (NPM1mut) and few other subtypes are dependent on downstream MEIS/HOXA activation for leukemogenesis and are amenable to menin inhibition." (PMID 41310838, 2025). "The KMT2A gene encodes histone-lysine N-methyltransferase 2A, also known as acute lymphoblastic leukemia 1 (ALL-1), myeloid/lymphoid, or mixed-lineage leukemia 1 (MLL1)." (PMID 38473304, 2024). "KMT2A mutations arise in 80% of acute lymphoblastic leukemia (ALL) and, together with mutations related to NPM1, in 30% of acute myeloid, lymphoid or mixed phenotype leukemia (AML)." (PMID 37816719, 2023). "Childhood KMT2A rearranged acute lymphoblastic leukemia (ALL) is associated with a poor prognosis, and there are multiple different KMT2A fusion partners." (PMID 35158889, 2022). "The translocation t(v;11q23) causes rearrangements of KMT2A, responsible for KMT2A-resistent (KMT2Ar) acute lymphoblastic leukemia (ALL)." (PMID 29879107, 2018). "KMT2A abnormalities are observed in 5–15% of the cases of acute lymphoblastic leukemia (ALL) and in 3% of adult patients with AML." (PMID 40647396, 2025). "In contrast to the male skew in cancers associated with loss of H3K27me3-repressive marks, loss of mixed-lineage leukemia 1 (MLL1 or KMT2A) expression through chromosomal translocation results in loss of the activating mark H3K4me3 in acute lymphoblastic leukemia (ALL)." (PMID 38949020, 2024). "Genetic rearrangements of KMT2A with partner genes, producing KMT2A fusion proteins and driving KMT2A‐r acute lymphoblastic leukemia (KMT2A‐r‐ALL)." (PMID 39428967, 2024). "Chromosomal translocations involving the KMT2A (MLL) gene constitute the cytogenetic hallmark of acute lymphoblastic leukemia (ALL) diagnosed in infants (< 1 year of age), giving rise to an aggressive malignancy with high relapse rates and low event-free survival (EFS) chances of 30–40%." (PMID 37740239, 2023). "This study identified EGR3 as a regulator of B-lineage specification and commitment processes in the context of infant KMT2A::AFF1 acute lymphoblastic leukemia." (PMID 37100882, 2023). "We defined the landscape of aberrant fusion circular RNAs in infant acute lymphoblastic leukemia with KMT2A::AFF1 translocations." (PMID 36585787, 2023). "The KMT2A::AFF1 (MLL::AF4) translocation is common in patients with MLL rearranged acute lymphoblastic leukemia and marks an aggressive subtype of infant disease." (PMID 36585787, 2023). "The molecular heterogeneity of KMT2A-rearranged infant acute lymphoblastic leukemia (ALL) remains poorly characterised." (PMID 36042201, 2022). "Infants with KMT2A-rearranged B-cell precursor acute lymphoblastic leukemia (ALL) have poor outcomes." (PMID 33937032, 2021). "KMT2A is commonly rearranged in both pediatric and adult acute lymphoblastic leukemia (ALL) and AML." (PMID 32727569, 2020). "KMT2A rearranged infant acute lymphoblastic leukemia patients have a poor prognosis." (PMID 36781850, 2023). "Although this model did lead to development of AML, or less commonly acute lymphoid leukemia, there are known effects of Kmt2a haploinsufficiency during murine development that cannot be controlled using this method, such as anemia, thrombocytopenia, and decreased B-cells." (PMID 35756660, 2022).
acute lymphoblastic leukemia (continued). "Besides, histone-modifiers of the KMT2 (histone-lysine N-methyltransferase 2) family are also frequently associated with the development of cancer, in particular KMT2A/MML1 (mixed lineage leukemia 1), which dearrangement leads to an oncogenic fusion protein in acute lymphoblastic leukemia." (PMID 41035915, 2025). "KMT2A-rearranged (KMT2A-r) acute lymphoblastic leukemia (ALL), particularly in infants, represents one of the most aggressive pediatric hematological malignancies with a historically dismal prognosis." (PMID 41614752, 2025). "Unbiased kinome-wide CRISPR screening identified DYRK1A as a potential therapeutic target in KMT2A-rearranged (KMT2A-R) B-acute lymphoblastic leukemia (ALL)." (PMID 40148558, 2025). "The most frequent structural variation of KMT2A in AML and acute lymphoblastic leukemia (ALL) is KMT2A-rearrangement (KMT2A-r), which is present in 10% of hematologic malignancies." (PMID 39303915, 2024). "In KMT2A-rearranged acute lymphoblastic leukemia (ALL), an aggressive malignancy, oncogenic KMT2A-fusion proteins inappropriately recruit DOT1L to promote leukemogenesis, highlighting DOT1L as an attractive therapeutic target." (PMID 37740239, 2023). "Chromosomaltranslocations involving KMT2A are responsible for some cases ofde novo acute lymphoblastic leukemia (ALL) and acute myeloidleukemia (AML)." (PMID 26657054, 2015). "KMT2A‐r‐ALL, as a subtype of acute lymphoblastic leukemia, predominantly affects lymphoid cells." (PMID 39428967, 2024). "In acute lymphoblastic leukemia (ALL), chromosomal translocations involving the KMT2A gene represent highly unfavorable prognostic factors and most commonly occur in patients less than 1 year of age." (PMID 37686014, 2023). "Acute lymphoblastic leukemia (ALL) in infants (i.e., children < 1 year of age) is frequently driven by chromosomal translocations of the mixed lineage leukemia (MLL or KMT2A) gene, which occur in ~80% of the cases." (PMID 34304246, 2022). "For example, only 75% of T-cell acute lymphoblastic leukemia (T-ALL) patients achieve remission, and patients with the B-cell acute lymphoblastic leukemia (B-ALL) subtypes of BCR-ABL1, BCR-ABL1 like, and KMT2A (MLL) rearranged have a high risk of treatment failure and poor prognosis." (PMID 35087776, 2021). "Here, we discovered that KMT2A regulated the cell viability, cell migration and cell apoptosis in cervical cancer, which has been certificated in melanoma and acute lymphoblastic leukemia (ALL)." (PMID 32436862, 2020). "Translocation of the KMT2A gene, better known as the MLL gene, is present in 7–10% of B acute lymphoblastic leukemias, AFF1 (or AF4) being the most frequent partner gene." (PMID 28535805, 2017). "Among the four H3K4 methyltransferase genes with similar structural domains, KMT2A (formerly named MLL) is frequently involved in genetic alterations in acute myeloid and acute lymphoblastic leukemia." (PMID 24240169, 2013). "In acute lymphoblastic leukemia (ALL) cell lines, and xenograft models, we observed increased DNMT1, and KMT2A expression in response to decitabine‐induced demethylation." (PMID 39754404, 2025).
myeloid leukemia (35 papers, 2006 to 2025). A clonal proliferation of myeloid cells and their precursors in the bone marrow, peripheral blood, and spleen. "Inappropriate activation of KMT2A, often due to chromosomal rearrangements, contributes to the development and progression of acute lymphoid and myeloid leukaemias." (PMID 38888967, 2024). "The human Trithorax gene MLL1 (mixed-lineage leukemia 1; also known as KMT2A) was first identified in gene translocations associated with aggressive lymphoid and myeloid leukemia." (PMID 38353483, 2024). "Mutations in ATM, MGA, KMT2A, MLLT10, NSD1, and TET2 have been commonly identified in several hematological neoplasms, including both acute lymphoid and myeloid leukemia." (PMID 38672648, 2024). "This gene is an important oncogenic target of aberrantly fused chromatin activator KMT2A in both lymphoid and myeloid leukemias." (PMID 36233173, 2022). "TALE-class homeobox gene MEIS1 is a well-known oncogene aberrantly activated via KMT2A-fusion proteins in both lymphoid and myeloid leukemias." (PMID 36233173, 2022). "KMT2A has been found to be early drivers of oncogenesis in aggressive lymphoid and myeloid leukemias." (PMID 31090199, 2019). "Notably, the Kmt2a-Mllt1 myeloid leukemia can be established in the Pax5 +/− background with similar dynamics as in the Pax5 +/+ background confirming that a reduced Pax5 gene dosage does not influence the leukemogenic activity of Kmt2a-Mllt1." (PMID 33134860, 2020). "The KMT2A gene, also known as MLL (Mixed Lineage Leukemia), plays a critical role in the pathogenesis of myeloid leukemias through its involvement in chromatin modification and gene expression regulation." (PMID 40374809, 2025). "The KMT2A (MLL) gene is located on chromosome 11q23 and can be rearranged with more than 80 different partner genes, which are seen in both lymphoid and myeloid leukemia." (PMID 33946897, 2021).
breast carcinoma (29 papers, 2010 to 2025). "When the transcriptional complex function of KMT2A is inhibited by mm102 in fibrotic fibroblasts, the changes in H3K4me3 modification are enriched in pathways related to aberrant transcription of oncogenes, genes associated with renal cell carcinoma, breast cancer and basal cell carcinoma." (PMID 39888275, 2025). "Recently it has been demonstrated that Sp1 interacts with the epigenetic enzyme KMT2A in the breast cancer cell line MCF7 cells." (PMID 34899171, 2021). "To this end, we determined how the small molecule inhibitor MI-503 disrupts the menin-KMT2A interaction that negatively influences downstream ATP production in breast cancer cells." (PMID 32971831, 2020). "Specific targets of KMT2/MLL epigenetic regulation have been shown to include hTERT (KMT2A, in melanoma), several HOX genes (KMT2A), ERalpha target genes in breast cancer (KMT2D), and androgen receptor target genes in prostate cancer (MLL1 and WDR5)." (PMID 29925347, 2018).
Wiedemann-Steiner syndrome (29 papers, 2014 to 2026). "Here we report a case of a Japanese girl with Wiedemann-Steiner syndrome carrying a novel heterozygous frameshift variant of KMT2A (NM_001197104.2:c.10123del, p.Thr3375ProfsTer7)." (PMID 41844570, 2026). "Heterozygous KMT2A variants cause Wiedemann-Steiner syndrome (MIM 605130), which is characterized by DD, ID, and characteristic facial features, with or without additional congenital anomalies." (PMID 40420380, 2025). "Although DDH has been classified as one of the musculoskeletal manifestations of the Wiedemann-Steiner syndrome, it has only been described in two Wiedemann-Steiner syndrome patients with exons 2–10 deletion and de novo nonsense mutation, p.Gln 1978* of KMT2A." (PMID 39156961, 2024). "Wiedemann-Steiner syndrome (WDSTS) is a neurodevelopmental disorder caused by de novo mutation of lysine methyltransferase 2A (KMT2A, a multidomain histone methyltransferase)." (PMID 39139810, 2024). "Haploinsufficiency of mixed-lineage leukemia (MLL/KMT2A) protein causes Wiedemann-Steiner syndrome (WSS), a neurodevelopmental disorder associated with microcephaly." (PMID 39661677, 2024). "Examples of this category include one boy with a phenotype consistent with Wiedemann-Steiner syndrome (MIM: 605130) in whom a de novo inversion/loss disrupting KMT2A (MIM: 159555) was detected (Family 5)." (PMID 38776926, 2024). "KMT2A germline mutations have a well-established association with Wiedemann-Steiner Syndrome (WDSTS, OMIM#605130)." (PMID 39303915, 2024). "Loss of function variants (LoF) in the KMT2A gene are associated with Wiedemann-Steiner syndrome (WSS, OMIM#605130)." (PMID 39156017, 2024). "Wiedemann-Steiner syndrome (WSS) is a rare autosomal dominant disorder caused by deleterious heterozygous variants of the KMT2A gene located on chromosome 11q23.3." (PMID 37025457, 2023). "Wiedemann-Steiner syndrome (WSS) is a rare Mendelian disorder of the epigenetic machinery caused by heterozygous pathogenic variants in KMT2A." (PMID 36062544, 2023). "Wiedemann-Steiner syndrome (WDSTS) is a neurodevelopmental pediatric disorder caused by the genetic disruption of the histone methyltransferase KMT2A." (PMID 35727845, 2022). "Wiedemann-Steiner syndrome (WSS) is a rare genetic disorder caused by mutation in KMT2A and characterized by neurodevelopmental delay." (PMID 36313433, 2022). "Wiedemann-Steiner syndrome (WDSTS) is a neurodevelopmental disorder caused by de novo variants in KMT2A, which encodes a multi-domain histone methyltransferase." (PMID 35727845, 2022). "Variants in the KMT2A gene are associated with Wiedemann-Steiner syndrome (MIM: #605130), a neurodevelopmental disorder characterised by intellectual disability, hypertrichosis cubiti, short stature, and typical facial features." (PMID 36360260, 2022). "First, we provide strong genetic evidence that the domains most important for mediating the causal role of KMT2A in Wiedemann-Steiner syndrome are the CXXC domain and–to a lesser extent–the fourth and first PHD fingers." (PMID 35727845, 2022). "As KMT2A is known as the causative gene in Wiedemann-Steiner syndrome (WDSTS, OMIM#605130), this truncating variant was implied to be responsible for the manifestations of severe growth and developmental delay in patient #33." (PMID 34544473, 2021). "Mutations in KMT2A were reported to be associated with Wiedemann-Steiner syndrome (WDSTS; OMIM 605130), an extremely rare neurodevelopmental condition accompanied by microcephaly, short stature, autism-like phenotype, and aggression." (PMID 28665350, 2017). "The identified variant truncates the protein, abolishes the C-terminal SET domain required for histone methyltransferase activity, and is predicted to trigger nonsense-mediated mRNA decay, resulting in KMT2A haploinsufficiency-the primary pathogenic mechanism of Wiedemann-Steiner syndrome." (PMID 41844570, 2026).
Wiedemann-Steiner syndrome (continued). "Wiedemann-Steiner syndrome (WDSTS) is a rare genetic cause of intellectual disability that is primarily caused by heterozygous loss-of-function variants in the gene encoding the histone lysine methyltransferase 2A (KMT2A)." (PMID 40956618, 2025). "The remaining case loss-of-function de novo mutations include some Mendelian disease genes with an existing neurological association, such as NIPBL, which is known to cause Cornelia de Lange syndrome and KMT2A, which is known to cause Wiedemann-Steiner Syndrome." (PMID 26332131, 2015). "Genetic rescue of KMT2A during gestation rescues postnatal neurological dysfunction in a mouse model of Wiedemann-Steiner syndrome." (PMID 40956618, 2025). "Wiedemann-Steiner syndrome (WDSTS; OMIM 605130), associated with mutations in KMT2A, is another extremely rare neurodevelopmental condition accompanied by microcephaly, short stature, autism-like phenotype, and aggression." (PMID 40469903, 2025). "Like ZMYND11, the gene encoding KMT2A is mutated in a neurodevelopmental disorder, Wiedemann-Steiner Syndrome (WSS), and KMT2A is also frequently mutated in cancer." (PMID 41279818, 2025). "Wiedemann-Steiner syndrome (WSS, MIM #605130) is a Mendelian Disorder of Epigenetic Machinery (MDEM) most often caused by haploinsufficiency of KMT2A, a gene encoding a histone methyltransferase that adds histone 3 lysine 4 (H3K4) methylation." (PMID 36062544, 2023). "Here, we show functional interactions of a writer-eraser duo, KMT2A and KDM5C, which are responsible for Wiedemann-Steiner Syndrome (WDSTS), and mental retardation X-linked syndromic Claes-Jensen type (MRXSCJ), respectively." (PMID 32483278, 2020). "The biological relevance of these proteins is highlighted by the clinical consequences of their haploinsufficiency, as KMT2A and TCF20 are the causative genes of Wiedemann-Steiner syndrome (WDSTS, OMIM #605130) and of a syndromic neurodevelopmental disorder (OMIM #618430), respectively." (PMID 35205380, 2022). "To date, 92 different mutations of KMT2A have been curated in the human gene mutation database (HGMD), resulting in Wiedemann-Steiner syndrome (WDSTS) and intellectual disability (ID)/developmental delay (DD)." (PMID 30841869, 2019). "We report the first case of a patient with Wiedemann-Steiner syndrome and PSIS, suggesting that the KMT2A gene may be related to pituitary development." (PMID 39156017, 2024).
prostate carcinoma (27 papers, 2016 to 2026). A carcinoma that arises from epithelial cells of the prostate gland. "Veterans with prostate cancer exhibited a mutational landscape broadly similar to prior studies, including KMT2A and NOTCH1 mutations associated with neuroendocrine prostate cancer phenotype, previously reported to be enriched in veterans." (PMID 38050021, 2023). "However, KMT2A expression was negatively correlated with these factors in 25 LuCaP patient-derived xenograft models of advanced prostate cancer and 99 laser-capture microdissected foci of metastatic castration-resistant prostate cancer." (PMID 36181613, 2022). "Our ChIP-seq analyses of genetically-modified prostate cancer cell lines suggested that KMT2A activity may positively mediate the tumorigenic function of MYC." (PMID 36181613, 2022). "Within the prostate-associated protein subset, CDK6 was the most connected node (14 edges), followed by ACVR2B, KMT2A, and PIK3R1, each with 13 edges (which ranks potential biomarkers and their impacts in prostate cancer)." (PMID 41598250, 2026). "Mechanistically, we observed that KMT2A and KMT2C differentially regulate the H3K4me1 and H3K4me2 in prostate cancer." (PMID 37345101, 2023). "Here, we report that in prostate cancer cells, differential binding of AR and HOXB13 on account of varying MYC levels centers on genes regulated by KMT2A/MLL1, which in turn is inversely proportional to the expression of PLA2G4F in cohorts of advanced, but not localized, PCa." (PMID 36181613, 2022).
myelodysplastic syndrome (22 papers, 2016 to 2025). A clonal hematopoietic disorder characterized by dysplasia and ineffective hematopoiesis in one or more of the hematopoietic cell lines. "KMT2A-PTDs are included in the IPSS-M prognostic model for myelodysplastic syndromes (MDSs), but are not yet included in current AML classifications." (PMID 39766070, 2024).
colorectal cancer (20 papers, 2007 to 2025). A primary or metastatic malignant neoplasm that affects the colon or rectum. "KMT2A can also interact with p65 and upregulate cathepsin Z, a known regulator of cancer progression in colorectal cancer." (PMID 39303915, 2024). "For example, a genome-wide loss-of-function screen examining the β-catenin signalling pathway identified KMT2A as a potential target and in vitro validation confirmed that two KMT2A-menin suppress β-catenin–active colorectal cancer cells." (PMID 34508276, 2022). "The histone methyltransferase KMT2A promotes colorectal cancer metastasis via activation of cathepsin Z." (PMID 34924998, 2021). "By analyzing KMT2A expression in patient tissues, we demonstrated that KMT2A was overexpressed in colorectal cancer tissues in comparison with adjacent normal tissues and its expression was positively correlated with cancer stages." (PMID 31090199, 2019). "Other research in colorectal cancer has shown similar connections between Notch activity, and KMT2A/MLL-1." (PMID 34944837, 2021). "Mechanistically, PCGF1 promotes the expression of the colorectal cancer stemness markers CD133, CD44 and ALDH1A1 by maintaining histone H3K4me3 and removing histone H3K27me3 marks by increasing the expression of the H3K4me3 methyltransferase KMT2A and the H3K27me3 demethylase KDM6A." (PMID 34148069, 2021).